PLK1 (polo like kinase 1)
Diseases named in the same sentence as PLK1 in open-access papers (continued):
Sharing a sentence is not in itself a finding about the gene and the disease.
tumor (continued). "This suggests a biologically relevant antitumor effect in a subset of patients, underscoring the promise of PLK1 inhibition while simultaneously highlighting the challenge of tumor heterogeneity and the need for predictive biomarkers." (PMID 41556056, 2026). "Evidence that PLK1 inhibitors (e.g., volasertib) can reduce tumor cell proliferation and migration, induce apoptosis, and sensitize cells to chemotherapy highlights the promise of PLK1 as an anticancer drug target." (PMID 41460629, 2025). "The pharmacological inhibition of IGF2BP2 suppresses tumor growth, offering a promising therapeutic strategy for PLK1-driven malignancies." (PMID 40347943, 2025). "Our findings of PLK1 overexpression in HCC align with previous studies showing its essential role in tumor cell proliferation." (PMID 40370109, 2025). "Since tumor heterogeneity gives rise to these subpopulations, we leveraged direct-capture Perturb-seq35 to identify SDL dependencies most effective at eliminating PLK1-overexpressing tumor cells." (PMID 40347943, 2025). "The survival rate of PC-3 tumor-bearing mice was highly elevated by NCs incorporating siRNA targeting polo-like kinase 1, which also highly suppressed the tumor growth in the absence of side effects from cation-associated toxicity." (PMID 40922741, 2025). "The TAT peptide facilitated nuclear targeting, leading to the knockout of Plk-1 and induction of apoptosis in tumor cells." (PMID 39942646, 2025). "PLK1 inhibitors exert their effects by suppressing the function of PLK1, thereby inhibiting tumor cell proliferation and inducing apoptosis." (PMID 40809688, 2025). "Through an extensive literature review, we found that many classical signaling pathways are involved in the process by which PLK1 leads to tumor proliferation, among which the MAPK, PI3K-AKT and NF-κB signaling pathways are the most widely reported." (PMID 41460629, 2025). "Mice with tumors treated with intranasal HA/DP7-C loaded with VEGF-specific and PLK1-specific siRNA showed reduced tumor growth, extended survival, and smaller tumor sizes." (PMID 41012513, 2025). "Using GEPIA (TCGA-OV tumors vs. GTEx normal ovary, log2 (TPM+1) normalization), we demonstrated that mRNA level of PLK1 in EOC tissues was much higher than that in normal ovarian tissues (tumor n = 426, normal n = 88, p < 0.05)." (PMID 41458961, 2025). "This revealed IGF2BP2 as a critical genetic dependency that, when targeted, downregulated PLK1 and significantly restricted tumor growth." (PMID 40347943, 2025). "The expression levels of pivotal regulatory genes (CDCA8, AURKA, and PLK1) were significantly higher in tumor samples than in control samples, whereas NR3C2 was significantly downregulated in cancerous tissues." (PMID 41357242, 2025). "Despite its predominant role as a tumor promoter, PLK1 can also exhibit tumor-suppressive effects under certain conditions." (PMID 40612941, 2025). "The behavior of plk1 as an oncogene or tumor suppressor is defined by the configuration provided by the tumor type and triggered dysregulations." (PMID 40430225, 2025). "In the present study, we observed BACH1 was highly expressed in PLK1 overexpressed cells and tumor samples." (PMID 41284701, 2025). "Key findings indicate that Episesamin targets and downregulates critical cell cycle genes CDK1, CDC25A, and PLK1, potentially inducing cell cycle arrest and inhibiting tumour growth." (PMID 40081286, 2025).
tumor (continued). "Accumulating evidence indicates that PLK1, beyond its well-established role in mitosis, exerts significant effects on the tumor microenvironment and is involved in tumor cell metastasis and immune cell infiltration." (PMID 40612941, 2025). "In PHOS3, increased phosphorylation of PLK1 was observed—a kinase shared with HCC that promotes tumor progression via metabolic and cell cycle–related pathways." (PMID 41296409, 2025). "Onvansertib is a novel ATP-competitive PLK1 specific inhibitor, which can induce mitotic cycle arrest and apoptosis in tumor cells." (PMID 40612941, 2025). "To further confirm PLK1’s role in vivo, we compared tumor proliferation and sensitivity to Vemurafenib treatment in a subcutaneous allograft." (PMID 41284701, 2025). "This suggests that the suppression of genome instability via the PLK1-mediated signaling pathway is likely a crucial aspect of DAB2IP’s ability to inhibit tumor development." (PMID 41261855, 2025). "Polo-like kinase 1 (PLK1) signaling drives tumor malignancy and chemotherapy resistance, which is an unmet clinical need." (PMID 40355412, 2025). "Recent studies have revealed that PLK1 inhibitors can synergize with PD-L1 immune checkpoint inhibitors in tumor immunotherapy." (PMID 40612941, 2025). "Increased PLK1 expression can inhibit the function of immune cells, such as NK cells and T cells, thereby promoting tumor immune escape." (PMID 40612941, 2025). "PLK1 also regulates inflammatory mediators and cellular effectors, thereby altering the local tumor microenvironment to promote tumor cell proliferation and survival while disrupting the adaptive immune response." (PMID 40612941, 2025). "The most common strategy in siRNA formulations is targeting proteins that act as key effectors in signaling pathways that regulate tumor growth, survival, and invasion (e.g., PLK1, PKN3, EphA2, KRAS, TGF-β1, COX-2, BCL2L12, VEGF, GSTP)." (PMID 41304746, 2025). "The use of a peptide vaccine that simultaneously targets PLK1 and blocks PD-L1 can lead to complete tumor eradication and long-term survival in mice with clonal heterologous C1498 myeloid leukemia." (PMID 40612941, 2025). "PLK1 is widely recognized for its oncogenic properties, given its critical role in driving cell cycle progression in tumor cells." (PMID 41261855, 2025). "First, we examined the protein expression of PLK1 in three stable LC cell lines and subcutaneous tumor tissues, and the results revealed a significant positive correlation between TRIM47 and PLK1 protein expression levels." (PMID 41460629, 2025). "In previous studies, PLK1 was shown to be involved in ferroptosis in tumour cells and played a key role in promoting tumour cell growth." (PMID 40462502, 2025). "We believe it is necessary to consider the role of Plk1 during the S phase more carefully in tumor development." (PMID 39883014, 2025). "Both B4 and combination therapy groups effectively reduced the positivity rate of PLK1 in tumor tissues, indicating that PLKi effectively regulated its targets in both drug-resistant and non-drug-resistant tumors." (PMID 40355412, 2025). "In light of this finding, we attempted an innovative pharmacological combination targeting both BRAFV600E and PLK1, identifying a synergistic efficiency to this approach to suppress tumor growth." (PMID 41284701, 2025). "Among them, PLK1 is the most widely studied protein, which plays a key role in cell cycle control, apoptosis and tumor development." (PMID 41460629, 2025). "Depending on the tumor context, plk1 either synergizes with carcinogenic events or promotes cell death." (PMID 40430225, 2025). "We subsequently extended this finding to in vivo models, where we observed effective tumor growth inhibition by three different PLK1 inhibitors, namely, rigosertib, volasertib, and onvansertib." (PMID 39941812, 2025).
tumor (continued). "In contrast to mMC cells, PLK1 overexpressed mMPI cells showed promoted tumor growth, significantly shortened doubling time, and limited response to Vemurafenib." (PMID 41284701, 2025). "This interaction promotes PLK1 activation, thereby supporting the survival and proliferation of tumor cells." (PMID 41282486, 2025). "PLK1 is overexpressed in a variety of tumor cells, especially in drug-resistant cells, resulting in tumor progression and tumor resistance." (PMID 40355412, 2025). "Although PLK1 inhibition in experimental models has shown potent antitumor effects, translation to the clinic has been hampered by low antitumor activity and tumor relapse." (PMID 39658088, 2025). "PLK1 is often regarded as a key oncogenic protein because of its critical function in promoting tumor cell division." (PMID 40581078, 2025). "PLK1 is a driver protein in tumor DNA repair, cell death pathways, and epithelial-to-mesenchymal transition." (PMID 39353904, 2024). "Blocking PLK1 expression with antibodies, RNA interference (RNAi), or kinase inhibitors has been found to reduce tumor cell proliferation and induce apoptosis." (PMID 38717954, 2024). "We found that patients with high PLK1 displayed lower M1/M2 ratio, indicating that these patients had more M2 macrophages in the bulk tumor samples." (PMID 38885192, 2024). "Recent studies have unveiled that targeting PLK1 improves the efficacy of immunotherapy, highlighting its important role in the regulation of tumor immunity." (PMID 38885192, 2024). "Here, using single-cell RNA sequencing (scRNA-seq), we show that elevation of PLK1 incurs a suppressive TME in LUAD, marked by M2 polarization of tumor associated macrophages (TAM) and suppression of antigen presentation process." (PMID 38885192, 2024). "This approach was used to treat melanoma by designing sgRNA targeting Polo-like kinase–1 (Plk1) in a tumor." (PMID 39339233, 2024). "TAT peptides guide the plasmids into the nucleus, thereby effectively targeting and knocking out Plk–1 in tumor cells." (PMID 39339233, 2024). "A recent study has demonstrated that the overexpression of AURKA, CDK1, and PLK1 is positively correlated with tumor grades and stage." (PMID 38672246, 2024). "Several possibilities have been proposed to explain the limited antitumor activity of PLK1 inhibitors in clinical studies, including the short half-life and low accumulation of PLK1 inhibitors in tumor tissues." (PMID 39085197, 2024). "PLK-1 expression has been positively correlated with aggressive tumor growth and poor prognosis in multiple solid and liquid tumors, including those of the head and neck." (PMID 38540116, 2024). "This is consistent with the known prognostic implications of elevated TTK and PLK1 expression, as well as the high levels of aneuploidy and CIN associated with this tumor type." (PMID 39184047, 2024). "On the other hand, in colon cancer cells expressing a truncated form of APC (APC-ΔC), PLK1 appears to have a tumor-suppressive function." (PMID 39273409, 2024). "Clinical trials have demonstrated the effectiveness of PLK1 inhibitors in reducing tumor growth, although challenges such as resistance mechanisms and off-target effects remain." (PMID 39473450, 2024). "A recent study further demonstrated the physical interaction of SHCBP1 with PLK1 in mitotic cells to promote tumour cell mitosis through an SHCBP1-PLK1-MISP axis." (PMID 38365687, 2024). "Other studies have shown that BP can directly combine with PLK1 to mediate the deactivation of centrosome kinase polo-like kinase 1 (PLK1), affecting mitosis during the cell cycle and promoting tumor cell apoptosis." (PMID 38609922, 2024). "This underscores the therapeutic potential of targeting PLK1 not only to counteract chemoresistance but also to impair CSC-driven tumor regeneration." (PMID 39451218, 2024). "Nevertheless, our understanding of the intricate interplay between PLK1 and the tumor microenvironment (TME) remains incomplete." (PMID 38885192, 2024).
tumor (continued). "This resulted in the reduced expression of PLK1, which led to cell death, tumor growth reduction, G2/M cell cycle arrest, and extended survival." (PMID 39339205, 2024). "This suggests that PLK1 helps to maintain the mitotic checkpoint in these cells, and its inhibition can accelerate the development of adenomatous polyps, supporting a “tumor-suppressor function” for PLK1 in APC-ΔC-expressing colon cells." (PMID 39273409, 2024). "A number of PLK1 inhibitors have been identified but most of these molecules displayed limited anti‐tumour activity and poor selectivity in preclinical models." (PMID 38264947, 2024). "This is noteworthy considering the strong positive correlation between high PLK1 expression and tumor occurrence." (PMID 38570712, 2024). "The observed association between PLK1 expression, ERK1/2 phosphorylation, and aggressive tumor behavior in our patient cohort further supports the potential of ERK1/2 inhibitors as a therapeutic option in PLK1-driven tumors." (PMID 39451218, 2024). "Consistently, Ki67, MMP2, MMP9, c-Myc, β-catenin, CDK4, CDK6, and Cyclin D1 protein levels in tumor tissues were significantly decreased by SAMD5 overexpression but partially increased by PLK1 overexpression." (PMID 39524172, 2024). "SAMD5 overexpression significantly decreased tumor weight and volume, whereas PLK1 overexpression partially attenuated these effects." (PMID 39524172, 2024). "Preclinical studies show that blocking PLK1 pathways effectively suppresses tumor cell growth and induces apoptosis." (PMID 39763588, 2024). "Significant tumor regression was detected in a mouse xenograft model treated with the PLK1 inhibitor, BI2536, compared with untreated controls, supporting a combined effect of PLK1 and MYC in tumorigenesis." (PMID 37450923, 2024). "In vivo, PLK1 also partially abolished the effects of SAMD5 overexpression in inhibiting tumor growth and the c-Myc signaling in a mouse model, providing further evidence for the in vitro findings." (PMID 39524172, 2024). "Polo-like kinase 1 (PLK1) is preclinically considered a functional regulator in multiple critical cell events during tumor progression." (PMID 38273295, 2024). "In another study, it was discovered that PLK1 is essential for controlling tumor autophagy, and blocking PLK1 activity can restrict tumor growth by regulating autophagy." (PMID 38393054, 2024). "According to some studies, inhibiting the expression of PLK1 by antibodies, RNA interference, or kinase inhibitors is effective in inhibiting tumor cell proliferation and inducing cell death." (PMID 39628476, 2024). "In a xenograft model, combining a PLK1 inhibitor with paclitaxel significantly decreased tumor volume compared to single-agent paclitaxel." (PMID 39473450, 2024). "This highlights the key role of the ERK1/2 pathway and Zeb1 in driving both therapeutic resistance and tumor stemness in PLK1-driven tumors." (PMID 39451218, 2024). "As predicted, mice treated with PLK1 knockdown vectors exhibited significantly reduced tumour growth compared with control mice receiving empty vectors." (PMID 38780513, 2024). "In vivo experiments demonstrated that SAMD5 overexpression led to a marked reduction in tumor weight and volume, effects that were partially reversed by PLK1 overexpression." (PMID 39524172, 2024). "The expression levels of KIF2C, CENPA, CDC20, UBE2C, ESPL1, KIF23, and PLK1 were significantly higher in the tumor tissues of patients with a HOST-response compared to those without a HOST-response." (PMID 39201599, 2024). "Taken together, the results revealed that the cell cycle regulator PLK1 and its substrate MISP promoted lymphatic invasion and tumor growth and repressed E-cadherin adherens junctions, demonstrating the crucial role of PLK1 and MISP in iCCA aggressiveness." (PMID 38057358, 2024). "As expected, AURKB, CCNA2, and PLK1 were upregulated in the tumor cell line compared to that in normal gastric epithelial cells." (PMID 37238607, 2023).
tumor (continued). "GSEA analysis further corroborated the GO/KEGG enrichment results, while enrichment in RHO gtpases also indicated the involvement of PLK1 in multiple processes in tumour growth, including mitosis, cell death, immunosuppression, and drug resistance." (PMID 37744268, 2023). "Because PLK1 regulates cell motility, it suggests that in addition to inhibiting cell proliferation, targeting PLK1 reduces tumour-cell migration." (PMID 37648284, 2023). "Accumulating evidence implies that PLK1 inhibition can promote the apoptosis of GSCs and can suppress tumor growth." (PMID 36805592, 2023). "MYC-amplified tumours often have upregulated PLK1, which creates a feed-forward interaction with Myc that maintains high levels of both proteins, predicting poor prognosis." (PMID 36902175, 2023). "This study confirmed that hsa-miR-100-5p is a tumor-suppressing miRNA targeting the well-known oncogene PLK1." (PMID 38201556, 2023). "Positive signals for PLK1 and p-PLK1 were localized in the nucleus, with 100% positive expression in tumor cells among the 40 NKTCL patients." (PMID 38037110, 2023). "We propose that PLK1 inhibitors should be given early in patients with HCC to reduce tumour invasion and metastasis." (PMID 37648284, 2023). "Polo-like kinase 1 (PLK1) is frequently found overexpressed in a variety of tumours, participates in DNA damage response, autophagy, apoptosis and cytokine signal, and is associated with poor prognosis." (PMID 37469408, 2023). "In MNA tumours, the inhibition of PLK1 by volasertib is correlated with a decrease in Myc protein levels." (PMID 36902175, 2023). "Further, in cell culture we demonstrate the feasibility of this strategy to cooperatively regulate gene expression of PLK1 to inhibit tumor cell proliferation, responding to orthogonal protein-signal stimulation." (PMID 37580346, 2023). "PLK1 is upregulated in various tumor entities, indicating oncogenic activity, but evidence of PLK1 functioning as a tumor suppressor has been published as well." (PMID 37183219, 2023). "Inhibited PLK1 activity leads to multiple mitotic defects, including the formation of abnormal spindles, misaligned chromosomes, and improper chromosomal condensation; while aberrant expression of PLK1 can induce diverse human tumor cell types." (PMID 36813765, 2023). "We also showed that knockdown of PLK1 in MDA-MB-231 cells delayed tumor growth in vivo as observed by reduced tumor volume and weight." (PMID 38234395, 2023). "The ROC analysis of clinical traits age, gender, and tumor stage in the combined GSE31210 dataset showed that the AUC of risk score was 0.649, which also demonstrated the guiding effect of PLK1 on the prediction of patient prognosis." (PMID 37744268, 2023). "This signature consists of 5 genes (HOTAIR, PLK1, LAMA3, EDA2R, and IKZF3) that are closely linked to tumor development." (PMID 37904416, 2023). "PLK1 expression was significantly higher in the tumor tissues compared to the normal breast tissues in the TCGA-BRCA cohort (p < 2.2e−16), and correlated with lower survival rate (p = 0.0088)." (PMID 38186570, 2023). "It has been confirmed that PLK1 is overexpressed in various human malignant tumour tissues, and PLK1 expression level significantly correlates positively with tumour cell proliferation ability, metastatic potential and poor prognosis." (PMID 37664042, 2023). "In both PDX lines, PLK1 inhibition by Volasertib led to dramatic reduction in tumor size and weight." (PMID 37419907, 2023). "Accordingly, we surmised that high PLK1 expression in BRCA tissues can improve the efficacy of immunotherapy on account of increased tumor heterogeneity." (PMID 38186570, 2023). "PLK1 regulates its function by interacting with tumor-related proteins, affecting malignant biological behaviors such as tumor proliferation, invasion, and migration, and is associated with poor prognosis of the patients." (PMID 38037110, 2023).